RND3 (Rho family GTPase 3)
Description:
Binds GTP but lacks intrinsic GTPase activity and is resistant to Rho-specific GTPase-activating proteins.
Synonyms: ARHE; RHO8; RHOE; memB
Tractability: Small molecule: a structure with a bound ligand is known. Antibody: its Gene Ontology location is reachable by antibodies, with high confidence; UniProt places it where antibodies can reach, with medium confidence. PROTAC: ubiquitination databases record sites on it; its protein half-life has been measured.
Gene: Protein-coding gene on chromosome 2 (150,468,195 to 150,539,011, reverse strand). Ensembl gene ENSG00000115963.
Subcellular location: Golgi apparatus membrane
Pathways (Reactome):
Signal Transduction: RND3 GTPase cycle
Gene Ontology:
Molecular function: protein binding; GTP binding; GTPase activity; protein kinase binding; G protein activity
Biological process: actin cytoskeleton organization; actin filament organization; cell adhesion; regulation of actin cytoskeleton organization; small GTPase-mediated signal transduction
Cellular component: focal adhesion; cytosol; plasma membrane; Golgi membrane
Genetic constraint (gnomAD): Loss-of-function variants: 4 observed, 17.17 expected, observed/expected ratio (o/e) 0.23, 90% interval 0.11 to 0.53. The upper end of that interval is the gene's LOEUF score, 0.53, which puts it in group 2 of 6, group 1 being the genes least tolerant of losing a copy. Missense variants: 179 observed, 240.69 expected, observed/expected ratio (o/e) 0.74, 90% interval 0.66 to 0.84. Synonymous variants: 91 observed, 88.33 expected, observed/expected ratio (o/e) 1.03, 90% interval 0.87 to 1.23.
Homologues: Orthologues: chimpanzee RND3 (100% identical), guinea pig RND3 (100% identical), macaque RND3 (100% identical), mouse Rnd3 (100% identical), pig RND3 (100% identical), rat Rnd3 (100% identical), dog RND3 (99% identical), rabbit RND3 (99% identical), tropical clawed frog rnd3 (96% identical), zebrafish rnd3a (90% identical), zebrafish rnd3b (72% identical). Paralogues in human: RND2 (59% identical), RND1 (58% identical), RHOA (39% identical), RHOB (38% identical), RHOC (37% identical), RAC1 (35% identical), RAC3 (35% identical), RAC2 (33% identical), RHOF (33% identical), RHOG (33% identical), RHOQ (33% identical), RHOU (33% identical), and 10 more.
Diseases named in the same sentence as RND3 in open-access papers:
RND3 is named in the same sentence as 70 diseases in open-access papers, as found by Europe PMC text mining. Sharing a sentence is not in itself a finding about the gene and the disease. The quoted sentences say what the papers report.
gastric cancer (17 papers, 2013 to 2025). A primary or metastatic malignant neoplasm involving the stomach. "The most up-regulated gene RND3/RhoE (+ 235.6-fold) was previously associated with tumor invasion, metastasis and was reported as a potential marker of drug resistance of gastric cancer as well as relapse and prognosis for colorectal cancer cases." (PMID 33515271, 2021). "Besides, the attenuation of CMA caused by LAMP2A knockdown in gastric cancer cells hindered cell proliferation by promoting Rho Family GTPase 3 (RND3/RhoE) accumulation." (PMID 40083922, 2025). "It is known that hypoxia-inducible factor-1α (HIF-1α) directly binds to the Rnd3 gene promoter and drives its expression in gastric cancer cells." (PMID 38343633, 2024). "CMA degrades the antiproliferative protein RND3 (Rho family GTPase 3) to maintain the rapid proliferation of gastric cancer cells." (PMID 37509689, 2023). "RND3 is under-expressed in gastric cancer, hepatocellular carcinoma, and prostate cancer, while it is overexpressed in pancreatic cancer and non-small cell lung cancer." (PMID 35992780, 2022). "Upregulation of RND3 suppressed the cell proliferation of gastric cancer cells and arrested them in the G0/G1 phase of the cell cycle." (PMID 34790699, 2021). "Additionally, in gastric cancer, chaperone-mediated autophagy contributed to cell proliferation by targeting RND3." (PMID 34790699, 2021). "In addition, in gastric cancer cells, some members of the Rho family like RND3, are maintained in the cytosol by specific phosphorylation events, which in turn allow their interaction with CMA components followed by lysosomal degradation." (PMID 33643916, 2020). "In gastric cancer, RND3 promotes metastasis by enhancing expression of CXCR4." (PMID 27705942, 2016). "Another link between CMA and the cell cycle occurs with the Rho family GTPase 3 (RND3), an anti-proliferative protein degraded by CMA in gastric cancer cell lines." (PMID 36010638, 2022). "Rho family GTPase 3 (RND3), a member of the RND subfamily of the Rho GTPases, is also degraded by CMA in gastric cancer cell lines." (PMID 32971884, 2020). "Researchers demonstrated that Rnd3 is a novel substrate protein for CMA, and the degradation of Rnd3 by CMA pathway can maintain cell proliferation in gastric cancer." (PMID 28881704, 2017). "For example, Rnd3 is overexpressed in pancreatic cancer and NSCLC and under-expressed in prostate cancer and gastric cancers." (PMID 28881704, 2017). "However, various malignancies, including Colorectal Cancer (CRC), Gastric Cancer (GC), and Non-Small Cell Lung Cancer (NSCLC) exhibited RND3 upregulaation." (PMID 39719443, 2024). "In addition, ectopic miR-200c has been found to sensitize SGC7901/DDP resistance gastric cancer cells to DDP through inhibiting expression of E-cadherin, Rho family GTPase 3 (RhoE) and ZEB2." (PMID 32192494, 2020).
glioblastoma (15 papers, 2013 to 2024). The most malignant astrocytic tumor (WHO grade IV). "We then set to characterise RND3 expression in relation to glioblastoma sub-types and genetic mutations in key disease genes." (PMID 26132659, 2015). "It has also been reported that RND3 promotes Snail1 degradation and inhibits migration and invasion of glioblastoma cells, which also confirms Snail1’s role in glioma cells." (PMID 37863960, 2023). "Rnd3 is a member of the Rnd subfamily of atypical Rho GTPases that is overexpressed in several types of tumours, including glioblastoma, and has been shown to negatively regulate Rho/ROCK activity." (PMID 36496976, 2022). "RND3, which is a Rho GTPase, inhibits cell proliferation in glioblastoma cells by interfering with Rb inactivation." (PMID 31541175, 2019). "Two recent mouse studies revealed an indispensable role of Rnd3 in mouse neuron development, and we have reported that Rnd3 regulated 293T and glioblastoma cell proliferation both in vitro and in vivo through Notch1 signaling." (PMID 29207629, 2017). "In human glioblastoma, RND3 expression was found to be significantly decreased, which caused increased Notch-pathway activity and enhanced glioma cell proliferation." (PMID 27023521, 2016). "We recently observed that expression levels of small G protein RND3 (also called RhoE) were significantly decreased in glioblastoma patients." (PMID 27705942, 2016). "By screening human GBM specimens, we found that the expression levels of small GTPase RND3 positively correlated with the expression levels of E-cadherin and claudin, the glioblastoma migration biomarkers negatively regulated by Snail1." (PMID 27705942, 2016). "Forced expression of RND3 diminished Snail1 activity, which in turn impeded glioblastoma cell migration and invasion." (PMID 27705942, 2016). "Downregulation of RND3, however, enhanced Snail1 signaling, in which repressed E-cadherin and claudin expressions, therefore facilitated glioblastoma cell migration and invasion." (PMID 27705942, 2016). "In summary, we demonstrated that RND3 negatively regulate glioblastoma migration and invasion through a Snail1-dependent pathway." (PMID 27705942, 2016). "In contrast, downregulation of RND3 augmented Snail1 activity, and subsequently decreased E-cadherin expression, eventually promoted glioblastoma cell migration and invasion." (PMID 27705942, 2016). "The experiment was conducted by intracranial implantation of U251 glioblastoma cells with stable RND3 expression in nude mice." (PMID 27705942, 2016). "Amongst these, we show that RND3 is up-regulated in glioblastomas and is a key regulator of tumour proliferation, migration and invasion." (PMID 26132659, 2015). "Consistent with the xenograft mouse study, forced expression of RND3 inhibited human glioblastoma cell proliferation, while RND3 knockdown facilitated glioblastoma cell growth in cell culture." (PMID 26108681, 2015). "This provides us with an array of concording results that clearly point to a pro-tumour role of RND3 in glioblastoma." (PMID 26132659, 2015). "Here, we provide evidence to show that the expression levels of RND3 are significantly downregulated in human glioblastomas." (PMID 26108681, 2015). "The inhibitory effect of RND3 on glioblastoma cell proliferation was further confirmed in an alternative glioblastoma cell line, U87." (PMID 26108681, 2015). "We conclude that downregulation of RND3 is responsible for the enhancement of Notch activity that promotes glioblastoma genesis." (PMID 26108681, 2015). "Our work shows that down-regulation or overexpression of RND3 supports its role as a pro-tumour gene in glioblastoma controlling proliferation, migration and invasion using different glioma cell lines." (PMID 26132659, 2015). "Forced expression of RND3 repressed Notch signaling, which led to the inhibition of glioblastoma cell proliferation in vitro and tumor growth in the xenograft mice in vivo." (PMID 26108681, 2015).
glioblastoma (continued). "However, NICD, MAML1, and CSL protein levels were significantly decreased in U251 glioblastoma cells with RND3 overexpression." (PMID 26108681, 2015). "We found that RND3 expression was significantly decreased in human glioblastoma." (PMID 26108681, 2015). "The negative regulation of RND3 on HES1 was also detected in U87 glioblastoma cells." (PMID 26108681, 2015). "We also noticed that the transcription of key genes involved in inflammation, proliferation, angiogenesis and extracellular matrix remodelling (including MMP2, HIF1A, IL1B, IL1A, IL1R1, MMP2, VEGFA), processes vital to glioblastoma development, were down-regulated by RND3 knock-down." (PMID 26132659, 2015). "Forced expression of RND3 inhibited Snail1 activity, which in turn blocked glioblastoma cell migration and invasion in vitro in cell culture and in vivo in GBM xenograft mice." (PMID 27705942, 2016). "In human glioblastoma tissues serial sections from normal brain tissue to GBM tissue, significant decreases in RND3, E-cadherin and claudin protein levels were observed in human GBM tissues compared to normal brain tissues." (PMID 27705942, 2016). "To explore the relationship between RND3 expression and glioblastoma migration/invasion, we assessed the expression levels of RND3 along with two GBM migration biomarkers E-cadherin and claudin in human GBM tissues and normal brain tissues." (PMID 27705942, 2016). "To determine the inhibitory role of RND3 in gliomagenesis, we generated a human orthotopic GBM xenograft animal model by intracranial implantation of U251 glioblastoma cells in nude mice." (PMID 26108681, 2015). "To explore the relationship of RND3 expression levels and glioblastoma progression, we divided GBM patients into two groups: low and high expression levels of RND3 determined by quantitative image analysis with densitometry for immunohistochemistry." (PMID 26108681, 2015). "Nevertheless, other studies made in glioblastoma cells showed that RND3 is a negative regulator of NOTCH signaling, as RND3 mediates NICD1 protein degradation through promoting its ubiquitination." (PMID 38343633, 2024). "In fact, the overexpression of RND3, another member of RND subfamily, enhances the invasion of glioblastoma and is correlated with a poor prognosis." (PMID 30333910, 2018). "However, previous studies in different tumor cells, how the RND3 repress the snail activity remains largely unknown.In addition to this evidence, our study provides evidence that RND3 is a novel repressor of Snail1 signaling and glioblastoma migration and invasion." (PMID 27705942, 2016). "The colocalization of endogenous RND3 with NICD, CSL, and MAML1 were visualized in U251 glioblastoma cells by immunofluorescent staining." (PMID 26108681, 2015). "We found that cotransfection of the reporter and RND3 expressing vectors led to a 66% reduction in luciferase activity compared to the baseline control without RND3 coexpression in U251 glioblastoma cells." (PMID 26108681, 2015). "Moreover, downregulation of RND3 in glioblastoma patients promotes tumorigenesis through augmentation of NOTCH complex transcriptional activity." (PMID 38343633, 2024).
melanoma (15 papers, 2010 to 2025). A malignant, usually aggressive tumor composed of atypical, neoplastic melanocytes. "The mechanism underlying our novel observation that WNT5A knockdown in these melanoma cells triggers a counteracting feedback response is a switch in RND3‐RhoA signaling." (PMID 33969605, 2021). "RND3 expression and function have been highlighted recently in cancers; however, there are limited studies in melanoma." (PMID 33969605, 2021). "RND3 expression is increased in invasive melanoma cells expressing BRAFV600E and is a known regulator of actin organization." (PMID 21917148, 2011). "We then constructed a doxycycline-inducible myc-tagged RND3 expression system to determine if reduced RND3 expression was required for melanoma invasion in the presence of BRAF inhibitors." (PMID 21917148, 2011). "Pinner and Sahai showed that a fine balance between PDK1 and Rnd3 expression is required for the amoeboid movement of melanoma cells, because the two proteins have opposing roles in controlling ROCK-I activity." (PMID 21209796, 2010). "Also, FOXD3 expression in melanoma cells downregulated migration and invasion by inhibiting Rnd3 expression, consistent with our results." (PMID 28430585, 2017). "This may result in a modulation of the tumor cell sensitivity to MAPK inhibitors, as demonstrated for RHOE/RND3, which impedes melanoma cell invasion in response to PLX4032." (PMID 26098773, 2015). "However, in some cancers, Rnd3 is up-regulated, such as in pancreatic tumors, colon cancer cell lines and some melanomas." (PMID 25372032, 2014). "The finding that Rnd3 promotes migration of cortical neurons through inhibition of RhoA activity was not surprising, because it uses the same mechanism to regulate the migration of fibroblasts, melanoma cells, and other cell types in culture." (PMID 21435554, 2011). "However, this impairment of WNT5A signaling appears to trigger a compensatory mechanism to maintain the invasive migration of BRAF wild‐type and BRAFV600 mutated melanoma cells treated with a BRAF inhibitor, through a RND3‐RhoA‐induced transition from a mesenchymal to an amoeboid mode of invasion." (PMID 33969605, 2021). "Thus, reduced RND3 expression supports melanoma invasion following BRAF inhibition." (PMID 21917148, 2011). "Recent work in a melanoma cell model suggested that, in addition to p190-RhoGAP regulation, ERK controls focal adhesion remodeling by curbing Rnd3 expression." (PMID 34071831, 2021). "For instance, RHOJ mediates melanoma cell resistance to dacarbazine, RAC1 is involved in breast cancer cell response to trastuzumab and RHOE/RND3 enhances multidrug resistance in gastric cancer cells." (PMID 26098773, 2015). "Accordingly, RND3 expression and suppressed RHOA signaling appear to be important for normal melanoma cell movement, whereas RND3 downregulation and enhanced RHOA signaling are critical in BRAF-inhibitor treated cells." (PMID 21917148, 2011). "Furthermore, in melanoma cells that persist after BRAF inhibition, Rnd3 restoration decreased cell invasion." (PMID 25538140, 2014). "Conversely, melanoma cell movement in the absence of BRAF inhibition was unaffected by RND3 expression or RHOA depletion." (PMID 21917148, 2011). "Thus, RND3‐RhoA signaling presents a possible compensatory mechanism in wild‐type BRAF and BRAFV600‐mutant melanoma cells treated with a BRAF inhibitor, suggesting that it could be a potential drug target in combination with WNT5A interference." (PMID 33969605, 2021). "The current study identifies novel roles for RND3 and RHOA in the movement but not growth or survival of melanoma cells treated with BRAF inhibitors." (PMID 21917148, 2011).
hepatocellular carcinoma (13 papers, 2013 to 2025). A malignant tumor that arises from hepatocytes. "Loss of RND3/RhoE in hepatocellular carcinoma enhances entosis through LAMP1 upregulation, implicating lysosomal activity in both initiation and degradation stages of the process." (PMID 40900810, 2025). "Here, we identified entosis in hepatocellular carcinoma and the loss of Rnd3 (also known as RhoE) as an efficient inducer of this mechanism." (PMID 38218945, 2024). "Rnd3 is down-regulated in many cancers, such as hepatocellular carcinoma, mesenchymal tumor cells, and prostate cancer." (PMID 25372032, 2014). "For example, silencing the NFE2L2 gene increased 5FU sensitization in hepatocellular carcinoma cells, RTN4 knockdown promoted higher cytotoxic events in paclitaxel-treated cancer cells, and RND3 overexpression promoted drug resistance in gastric cell lines." (PMID 36675023, 2023). "For instance, compared to non-tumoral liver tissues, Hepatocellular Carcinoma (HCC) tissues exhibited a lower RND3 expression at both the mRNA and protein levels." (PMID 39719443, 2024). "Indeed, RND3 expression is downregulated in human hepatocellular carcinoma (HCC) samples compared to non-tumoral liver tissues and correlated with poor survival rates." (PMID 38218945, 2024).